LRP1 (LDL receptor related protein 1)
Diseases named in the same sentence as LRP1 in open-access papers (continued):
Sharing a sentence is not in itself a finding about the gene and the disease.
prostate carcinoma (15 papers, 2011 to 2025). A carcinoma that arises from epithelial cells of the prostate gland. "In this study, expression of one of LRP1’s splice variants, referred to as “small LRP1” (smLRP1), that was initially detected in large lung cell and prostate carcinoma was investigated." (PMID 28662213, 2017). "In prostate cancer cells, eHSP90 binds to LRP1 and promotes ERK signalling, leading to the impairment of E-cadherin function, the loss of junctional integrity and the induction of EMT." (PMID 33544155, 2021). "As smLRP1 was first detected in lung and prostate carcinoma, 12 human tumour cell lines of different origin were screened for expression of smLRP1 and LRP1." (PMID 28662213, 2017). "We showed previously that PN1-uPA complexes preferentially signal through the LRP-1 to control SHH signalling in prostate cancer." (PMID 25686839, 2015). "In addition, LRP1 has been shown to promote EMT in prostate cancer cells." (PMID 34458332, 2021). "However, LRP-1 has been shown to mediate Hsp90-induced type 3 EMT in prostate cancer cells." (PMID 25514242, 2014). "Extracellular HSP90 interacts with LRP1 (also known as CD91) to induce ERK and MMP-2/9 activation, leading to E-cadherin inhibition and the initiation of EMT in prostate cancer cells." (PMID 39148727, 2024). "A subset of bone marrow samples that displayed a high frequency of CTC-IGC from the prostate cancer patient cohort were stained with HOMER1, TNFRSF9, and LRP1." (PMID 39483900, 2024). "Androgen receptor (AR)- and low-density lipoprotein receptor-related protein-1 (LRP1)-positive prostate cancer cell line, LNCaP is more sensitive to emodin than AR-negative LRP-positive prostate cancer cells, PC-3 cells." (PMID 34073059, 2021). "mRNA expression and western blotting indicated that, with the exception of LRP1 in 22Rv1, all components of the LRP1-Met-IQSEC1-ARF5/6 pathway are expressed in examined prostate cancer cell lines." (PMID 33712589, 2021). "In publicly available data for previously treated patients, high expression of TNFRSF9 and LRP1 significantly correlated with a shorter progression free survival in patients with prostate cancer; HOMER1 was not statistically significant (p-value = 0.183)." (PMID 39483900, 2024).
aneurysm (12 papers, 2009 to 2025). Bulging or ballooning in an area of an artery secondary to arterial wall weakening. "Genetic variation in LRP1 (low-density lipoprotein receptor-related protein 1) was reported to be associated with thoracic aortic dissections and aneurysms." (PMID 35050224, 2022). "To evaluate the extent to which dysregulated LRP1–PDGFR-β signaling predisposes to AngII-induced aneurysm, we sought to rescue the exacerbated phenotype of Tβ4–/Y mice by pharmacological inhibition of the pathway." (PMID 33784254, 2021). "Tβ4-null mice displayed aortic VSMC and elastin defects that phenocopy those of LRP1 mutants, and their compromised vascular integrity predisposed them to Angiotensin II–induced aneurysm formation." (PMID 33784254, 2021). "LRP1, which has been involved in aneurysm pathology in both humans and mice, appears to be linked to ADAMTS-5 and ADAMTS-5–mediated versican cleavage." (PMID 29622560, 2018). "In the present study, we have reconfirmed these Marfan syndrome-like phenotypes, including elastic layer disruption, aorta elongation, and aneurysm formation in the presence of increased Smad2 phosphorylation when LRP1 is deficient in the SMCs." (PMID 19742316, 2009). "Interestingly, LRP1 has been implicated in aneurysm formation; LRP1 deletion in SMCs profoundly augmented aneurysm formation in the ascending aorta (AsAo) induced by AngII." (PMID 29622560, 2018). "Previous studies have reported that genetic variants of LRP1 and the reduction in LRP1 protein expression may be associated with aneurysm progression." (PMID 24484584, 2014). "Mice in which the lrp1 gene is selectively deleted in vascular smooth muscle cells develop a phenotype similar to the progression of aneurysm formation in human patient, revealing that these mice are ideal for investigating molecular mechanisms associated with aneurysm formation." (PMID 25949827, 2015). "The objective of the current investigation was to define molecular mechanisms by which LRP1 protects against aneurysm formation in this vessel bed." (PMID 36472907, 2023). "A number of SNPs have been found through GWAS to be associated with SMC apoptosis in aneurysms, such as CDKN2BAS, DAB2IP, and LDL receptor-related protein 1 (LRP1)." (PMID 35207478, 2022). "LRP1 is a large endocytic signaling receptor that contributes to vascular development, exerts a role in lipoprotein metabolism, regulates protease concentrations, regulates inflammation, and attenuates the progression of atherosclerosis and aneurysm formation." (PMID 36472907, 2023). "In the vasculature, LRP1 also plays protective role from the development of aneurysms." (PMID 25949827, 2015). "Repressing LRP1 translational expression results in excess accumulation of matrix metalloproteinase (MMP) 9 in abdominal aortic vascular tissue, degrading the extracellular matrix components and consequently promoting aneurysm formation." (PMID 35050224, 2022).
aortic aneurysm (12 papers, 2007 to 2024). A ruptured aneurysm located in the wall of the proximal portion of the descending aorta proceeding from the arch of the aorta. "In humans, genome-wide association studies, exome sequencing, and TaqMan single nucleotide polymorphism (SNP) genotyping assays have identified an association of LRP1 SNPs with aortic aneurysms, aortic dissections, and Marfan syndrome." (PMID 36472907, 2023). "Genetic studies in humans have revealed that the LRP1 gene is a susceptibility locus for aortic aneurysms and dissections." (PMID 36472907, 2023). "LRP1 has previously been implicated in aortic aneurysm formation in humans and mice; however, the exact mechanisms are unclear." (PMID 29622560, 2018). "LRP1 encodes for low-density lipoprotein receptor-related protein 1 which is involved in several cellular processes, with additional genetic studies and mouse studies implicating LRP1 in aortic aneurysms." (PMID 37979122, 2023). "Since all our patients are suffered from aortic aneurysm and the new missense mutation of LRP1 is the only protein-altering variant we detected in this gene, it is possible that this damaging mutation results in dysfunction of the protein, contributing to the pathogenesis of aortic aneurysm." (PMID 24484584, 2014). "Disruption of LDL receptor-related protein-1 (Lrp1) in smooth muscle cells has been shown to cause vascular pathologies similar to Marfan syndrome, with activation of smooth muscle cells, vascular dysfunction and aortic aneurysms." (PMID 24312398, 2013). "Recent studies in mice have identified a critical role for the low-density lipoprotein receptor–related protein 1 (LRP1) in protecting against aortic aneurysms." (PMID 36472907, 2023). "Collectively, these data demonstrate that loss of Tβ4 predisposes to aortic aneurysm, phenocopying VSMC-specific LRP1 mutants." (PMID 33784254, 2021). "The resulting disruption of elastic layers, vascular fibrosis, elongation and distension of the aorta, and high incidence of aortic aneurysms directly support the pivotal role of TGFβ signaling in the pathogenesis of MFS and reveal LRP1 as a critical regulator of this pathway in vivo." (PMID 17505534, 2007).
pancreatic cancer (12 papers, 2018 to 2024). "This suggests that Hsp90α/LRP1 signaling plays a crucial role in the malignant transformation and treatment resistance of pancreatic cancer." (PMID 38727789, 2024). "The exosomal transfer of ANXA6 was found to facilitate pancreatic cancer aggressiveness by the formation of the annexin A6/LDL receptor-related protein 1/thrombospondin 1 (ANXA6/LRP1/TSP1) complex." (PMID 39684264, 2024). "Using TCGA datasets, we found that increased LRP1 expression significantly correlated with decreased patient survival in pancreatic cancer (p = 0.018, n = 176)." (PMID 35628341, 2022). "CAFs in pancreatic cancer form annexin A6/LDL receptor-related protein 1/thrombospondin 1 (ANXA6/LRP1/TSP1) complex, which is released in the form of extracellular vesicles (EVs), thereby enhancing the migratory capacity of cancer cells, which ingests EVs." (PMID 33050237, 2020). "The activation of PSCs was mediated by pancreatic cancer cells-derived PAI-1 acting through the LRP-1/ERK/c-JUN pathway." (PMID 31695760, 2019). "In pancreatic carcinoma, high stromal expression of LRP1 was correlated with a decreased activation of caspase 3 in tumor cells and increased level of SNAIL, a transcription factor promoting epithelial-mesenchymal transition and cell migration." (PMID 29507659, 2018). "Hsp90α promotes metastasis and chemoresistance in pancreatic cancer through its receptor LRP1." (PMID 38727789, 2024). "Specific membrane proteins such as CD151 and Netrin-1, along with the ANXA6/LRP1/TSP1 complex, further enhance the invasiveness and migration capabilities of pancreatic cancer cells by participating in cell–cell interactions and signaling transduction." (PMID 38954230, 2024). "For this, we exposed human pancreatic cancer cell lines (PANC-1, RWP-1 and Capan-1) to native (nLDL) or AgLDLs in the absence or presence of LRP1-based peptides (DP3) or irrelevant peptides (IP321)." (PMID 35205638, 2022). "Low-density lipoprotein receptor-related protein-1 (LRP1) reportedly acts as a receptor for hemopexin, and its expression on pancreatic cancer cells was confirmed." (PMID 32663208, 2020). "Similarly, expression levels of MIF and LRP1 showed significantly negative correlation in 196 pancreatic cancers from TCGA using UCSC Xena database (Pearson’s rho r = -0.3718, P = 2.204e-7)." (PMID 36703790, 2022).
dementia (11 papers, 2014 to 2025). Loss of intellectual abilities interfering with an individual's social and occupational functions. "The aim of this study was to assess the usefulness of ABCA1, ABCB7, ABCB1, APOE, CYP46A1, and LRP1 genotyping as promising dementia risk factors among a wide group of patients diagnosed first with hyperlipidemia." (PMID 41226793, 2025). "It was also found that PPAR-γ agonists were able to ameliorate learning and memory deficits in a mouse model of dementia by increasing the expression of low-density lipoprotein receptor-related protein 1 (LRP1) in the hippocampus." (PMID 40028337, 2025). "Also, LRP1 mRNA expression was positively correlated with clinicopathological hallmarks of AD, including dementia." (PMID 39273636, 2024). "The control cases without dementia showed only neuronal and astrocytic staining but no LRP1-positive senile plaques." (PMID 39273636, 2024). "Despite this fact, there are certain reports showing strong LRP1 immunoreactivity in senile plaques and reactive astrocytes in AD subjects, while there is strong immunoreactivity in neurons and light immunoreactivity in astrocytes in patients without dementia." (PMID 39273636, 2024).
dyslipidemia (11 papers, 2012 to 2025). "In summary, this study showed that global dysfunction of LRP1 due to distal NPxY motif mutation is protective against HFHC diet-induced dyslipidemia, fatty liver disease, and neuroinflammation." (PMID 33500241, 2021). "Although the LRP1 rs1799986 polymorphism is implicated in the occurrence of AD and metabolic syndrome, and the C allele is found to be positively associated with AD susceptibility, the role of the LRP1 gene related with cognitive function is still conflicting." (PMID 33013281, 2020). "The common LRP1 polymorphism 677C > T, a single-nucleotide polymorphism (SNP) at the position 677 of exon 3 of the LRP1 gene (database identifier dbSNP ID: rs1799986), is involved in AD and metabolic syndrome development." (PMID 33013281, 2020). "In our study, the CT genotype distribution of rs11172113 in LRP1 was found to be significantly higher in dyslipidemia male cases vs controls." (PMID 37147786, 2023). "In subsequent studies, a positive association between DNA methylation in LRP1 gene and HDL-CH level was demonstrated in patients with metabolic syndrome." (PMID 33028190, 2020). "Dyslipidemia emerges early in CKD, distinguished from the MAFLD pattern by reduced activity of LPL and hepatic lipase, down-regulation of VLDL receptors (VLDLR) in muscle and adipose tissue, and diminished hepatic LDL-receptor-related protein 1 (LRP-1)." (PMID 40725208, 2025).
lung adenocarcinoma (11 papers, 2014 to 2024). A carcinoma that arises from the lung and is characterized by the presence of malignant glandular epithelial cells. "Additionally, a lower expression of LRP1 in lung adenocarcinomas correlates with less favorable clinical outcomes, and higher levels correlate to more favorable clinical outcomes." (PMID 34281263, 2021). "More importantly, the expression of LRP1 is involved in the outcome of lung adenocarcinoma." (PMID 34819038, 2021).
brain tumors (10 papers, 2017 to 2025). "Recent literature suggests that low density lipoprotein receptor-related protein 1 (LRP-1) is the target of NPs which is upregulated in brain tumors and is present in the capillary endothelium of BBB." (PMID 37649926, 2023). "As such, heavily pursued therapeutic avenues have exploited LDL receptor-related protein-1 (LRP-1)-mediated capacity in internalizing Angiopep-2 (An2), a brain-penetrating peptide that allows An2–drug conjugates to cross the blood–brain tumor barrier (BBTB)." (PMID 36430705, 2022). "In this study, we found that membrane type-1 (MT1)-MMP expression increased from grade 1 to 4 brain tumors, while that of LRP-1 decreased inversely." (PMID 36430705, 2022). "Here, we provide evidence for differential genotypic MT1-MMP and LRP-1 biomarker expression between tissues from grade 1 to 4 brain tumors." (PMID 36430705, 2022). "Conjugation of Angiopep-2 into liposomes exhibited better targeting delivery to brain tumors via the low-density lipoprotein receptor-related protein-1 (LRP1) pathway." (PMID 34713363, 2021). "LRP-1 transcript levels appeared to inversely correlate with increasing brain tumor gradation." (PMID 36430705, 2022). "Another receptor is low-density receptor-related protein (LRP1); LRP1 is an excellent receptor to target with drugs for malignant glioblastoma since it is overexpressed broadly in both the blood–brain barrier and in the blood–brain tumor barrier." (PMID 36559214, 2022). "Understanding the mechanisms regulating LRP-1-mediated An2 internalization and its relation to MT1-MMP in brain tumors is relevant in optimizing drug delivery strategies for the treatment of GBM." (PMID 36430705, 2022). "We first assessed how LRP-1 and MT1-MMP expressions correlate with the malignancy and the invasiveness of the brain tumors as classified by the WHO grading system." (PMID 36430705, 2022). "Since Ap exhibited high affinity to LRP1, here we used Ap to decorate on the surface of glycolipid-like nanoparticles (Ap-CSSA/DOX) for BBB targeting and brain tumor cascade-targeting, thus realizing GBM effective therapy." (PMID 29182025, 2017). "Given the high LRP-1 transcript levels observed in low-grade brain tumor tissues, our data further indicate that a potential pool of LRP-1 may be available in those tumors, which would still contribute to LRP-1-mediated An2 uptake." (PMID 36430705, 2022).
Cerebral ischemia (10 papers, 2009 to 2025). Restriction of arterial blood supply to the brain associated with insufficient oxygenation to support the metabolic requirements of the tissue. "In addition, γ-secretase-mediated proteolysis of LRP1 has been implicated in cerebral ischemia-induced cell death." (PMID 31409872, 2019). "Emerging studies demonstrate that astrocytic LRP1 suppression impairs intercellular mitochondrial transfer to compromised neurons, consequently aggravating cerebral ischemia–reperfusion pathology." (PMID 40740686, 2025). "The data indicate that in the CA3 area of the hippocampus, an episode of brain ischemia causes the increased expression of the RAGE gene for 7–30 days during the acute phase and that of LRP1 from 1 to 24 months after ischemia during the chronic stage." (PMID 38067191, 2023). "The amount of α-chain of LRP1 was decreased, whereas that of a 17-kDa ICD, which is produced by cleavage at an intramembrane site of LRP1, was significantly increased in the ischemic areas of the ipsilateral hemisphere after cerebral ischemia." (PMID 31409872, 2019). "In the present study, we sought to determine the effect of cerebral ischemia in vivo on the level of LRP1 protein." (PMID 31409872, 2019). "The number of cells that LRP1-ICD was co-localized with TGN marker TGN46 was significantly increased in the ischemic areas of the ipsilateral hemisphere after cerebral ischemia." (PMID 31409872, 2019). "Our findings are the first to demonstrate that LRP1 was significantly cleaved by furin after cerebral ischemia in rats as well as after exposure of cultured cortical neurons to NMDA." (PMID 31409872, 2019). "In conclusion, our findings are the first to demonstrate that mature LRP1 is cleaved by furin after cerebral ischemia in rats and following NMDA exposure in cortical neurons in primary culture." (PMID 31409872, 2019). "The interactions between tPA and LRP1 or PDGFRα during cerebral ischemia increase the expression of MMP2 and MMP9." (PMID 30186167, 2018). "In vivo, when Lrp1 was conditionally ablated from microglia, the cells were less responsive to cerebral ischemia." (PMID 27280679, 2016). "LRP1 activation has been shown to attenuate oxidative stress, neuroinflammation and apoptosis and can improve short- and long-term neurological deficits and positively influence mortality after cerebral ischemia by inhibiting the TXNIP/NLRP3 signaling pathway." (PMID 38067191, 2023). "We conducted experiments to determine changes in the processing pathway of LRP1 in a rat model of cerebral ischemia and by examining cultured cortical neurons after NMDA receptor-mediated excitotoxicity, which has been implicated in a variety of neurodegenerative diseases." (PMID 31409872, 2019). "Additionally, LRP1 is expressed by perivascular astrocytes, and may be involved in the regulation of blood brain barrier permeability in the early stages of cerebral ischemia." (PMID 27280679, 2016). "Although a growing body of evidence indicates that LRP-1 plays a role in the pathophysiology of cerebral ischemia and deletion of LRP-1 in mouse is embryonic lethal, two important aspects of LRP-1 are still unclear." (PMID 19137075, 2009). "The level of β-chain of LRP1 was not altered after cerebral ischemia, although its molecular weight was shifted toward a lower one in the ischemic areas." (PMID 31409872, 2019). "Therefore, we pointed out a preventive role of RAGE in mediating Aβ1-40 clearance system contributing to transient cerebral ischemia with Aβ infusion deteriorated cognitive function, with the lacking of LRP-1-mediated clearance of Aβ from the brain." (PMID 32264971, 2020).